MYD88 (MYD88 innate immune signal transduction adaptor)
Diseases named in the same sentence as MYD88 in open-access papers (continued):
Sharing a sentence is not in itself a finding about the gene and the disease.
fungal infections (continued). "Thus, MyD88 signaling in myeloid cells plays an integral role in immunity against fungal infections." (PMID 26367276, 2015). "Moreover, Myd88−/− mice are susceptible to systemic fungal infections—including systemic candidiasis—however MYD88-deficient patients do not develop candidiasis or other fungal disease, likely due to compensatory effects of other PRRs, primarily of CLRs." (PMID 34964702, 2022). "Humans with a MyD88 signaling defect do not have a higher susceptibility to fungal infections." (PMID 32899547, 2020). "Even though the MyD88 allele we have tested has been extensively characterized in a previous study, a remote possibility remains that the phenotype we observe is due to a second-site mutation that would specifically impact the sensitivity to T. marneffei and not to other fungal infections." (PMID 39239739, 2024). "The absence of Gal-3, in fungal infection, a positively modulated gene involved in phagocytosis (sftpd) and negatively genes involved in signal transduction (syk and myd88), proinflammatory cytokines il-1β and il-12b and cd209a receptor." (PMID 34203011, 2021). "It has been reported that induction of Tc17 phenotype by CD8+ cells following fungal infections is dependent on Tlr2 and MyD88, while induction of Tc1 phenotype is not." (PMID 27252700, 2016). "However, the T cell-intrinsic role of MyD88 in adaptive immune responses to fungal infections has not been defined." (PMID 26367276, 2015).
Immunodeficiency (24 papers, 2008 to 2025). Failure of the immune system to protect the body adequately from infection, due to the absence or insufficiency of some component process or substance. "This study characterized two novel MYD88 DD variants (L35P and W47C) that expand the genetic spectrum of this rare immunodeficiency." (PMID 41479884, 2025). "For this, we expressed mTET2-R1261C in dTet-expressing cells with either Myd88, Relish, or Stat92E RNAi targeting the three main pathways that play a role in innate immunity: the Toll pathway, the immune deficiency pathway (IMD), and the JAK-STAT pathway." (PMID 36989121, 2023). "Autosomal recessive (AR) interleukin-1 receptor (IL-1R)-associated kinase 4 (IRAK4) deficiency, together with myeloid differentiation primary response gene 88 (MyD88) deficiency, is a primary immune deficiency that impairs IL-1R and TLR family signaling." (PMID 33083971, 2021). "Although these encouraging results suggest a potential therapeutic role of the TLRs inhibition in IIM, it is well known that the TLR2, TLR4 and MyD88 deficiency implies a severe immunodeficiency." (PMID 32164729, 2020). "Naturally occurring mutants of MyD88 that cause immunodeficiency are unable to form these structures." (PMID 30786893, 2019). "Two mutations in MyD88 that cause immune deficiency in humans were then tested for their effect on the propensity of full-length MyD88 to oligomerise." (PMID 30786893, 2019). "This study also identified immune disease-related genes associated with somatic mutations such as MYD88 and BCL10 in NF-κB signaling, CD79B, PAX5, and BCR in B-cell development, and MYH11, RUNX1, and TET2 in leukemia." (PMID 29937999, 2018). "Myd88 deficiency in mice results in several immune diseases." (PMID 32266286, 2020). "In the patient with MYD88 deficiency, the atypical presentation was characterized by chronic yersiniosis resulting in terminal ileitis and recurrent neutropenia, in the absence of invasive pneumococcal disease, as is expected in this rare immunodeficiency." (PMID 27872624, 2016). "The observation that the immunodeficiency of IRAK4- and MYD88-deficient children usually improves with age suggests a gradual compensation of the adaptive immune response with time or that the innate immune response is able to mature with age." (PMID 25886387, 2015). "In our population both primary and secondary immunodeficiencies were detected in 2 patients (and suspected in another): one patient was receiving chemotherapy and the other suffered an identified PID (MyD88 deficiency)." (PMID 25738983, 2015). "Clinical features resulting from LYST mutations in CHS have much in common with immunodeficiencies caused by TLR signaling defects, such as conditions caused by autosomal recessive mutations in TLR adapters, IRAK-4 and MyD88 (OMIM# 610799, 607676, 612260)." (PMID 25528552, 2014). "The detection of both variants within the tumor clone suggests that loss of function of one allele may potentiate the gain-of-function effect of the other, underscoring the dual role of MYD88 in both oncogenesis and immunodeficiency." (PMID 41479884, 2025). "Once the MyD88 signal is activated, this leads to a series of inflammatory response syndromes, which are mainly manifested by organ immune damage, atherosclerosis, and other immune diseases." (PMID 38785969, 2024). "IRAK4 and MYD88 deficiencies on the other hand appear to result in a narrow-spectrum immunodeficiency characterised by IPD and the absence of AED." (PMID 25886387, 2015). "Thus, although Dram1 enhances the immune response to Mm infection in the absence of Optn or p62, it cannot compensate for general immunodeficiency caused by disruption of Myd88-dependent innate immune signaling." (PMID 38264729, 2023). "Thus, modulation of that action of TLRs and MyD88 could provide potential therapeutic targets for the treatment of immune disorders." (PMID 19094215, 2008).
Immunodeficiency (continued). "As an anchoring adaptor protein, MyD88 processes and delivers the signals generated by the TLR and IL-1 receptor (TLR/IL-1R) superfamily and is crucial in innate immune disease." (PMID 37252680, 2023). "HZOL can reverse LPS-induced changes relating to the inflammatory cytokines and immune dysfunction and attenuating the expressions of TLR4, CD14, MyD88, NF-κB p65, and p-NF-κB p65 of the TLR4/NF-κB p65 pathway." (PMID 36845637, 2023). "B. breve CCFM1026 significantly reduced the proportion of neutrophils and increased lymphocytes, the expressions of TLR7, MyD88, TRAF6, and TNF-α to restore the immune disorders." (PMID 33924002, 2021). "Unlike Myd88 −/− mice where their immunodeficiency not only led to increased intestinal pathogen burdens, but also lethally high C. rodentium burdens in the liver and spleen, the Sigirr −/− mice only showed increased pathogen burdens in their ceca and colons." (PMID 23950714, 2013). "The patient could not recover because of his natural immune deficiency and TLR4/MyD88/NF-κB signaling pathway inactivation." (PMID 34454624, 2021).
glioma (22 papers, 2017 to 2025). A benign or malignant brain and spinal cord tumor that arises from glial cells (astrocytes, oligodendrocytes, ependymal cells). "The MYD88 gene was significantly over-expressed in the plasma samples of glioma patients; a depletion or deficiency of this cytosolic adapter protein has been previously shown to attenuate the expansion of glioma in animal studies." (PMID 34643804, 2022). "We found that macrophage M2 accounted for the largest portion with an average of 27.6% in the glioma TIICs and was associated with high expression of MYD88." (PMID 33898320, 2021). "Further analysis revealed that MYD88 was over expressed in gliomas and associated with the survival, WHO grade and TIICs especially the macrophage M2." (PMID 33898320, 2021). "In glioma patients, MYD88 lower expression was associated with significantly longer overall survival (p < 0.001)." (PMID 33898320, 2021). "Therefore, our research established an ICD-related score to investigate the potential effect to chemotherapy and immunotherapy for glioma patients and indicated that MYD88 was a key role in this risk model." (PMID 37456890, 2023). "Moreover, the authors discovered that MYD88 expression was higher in IDH1 wild types glioma and positively associated with M2 macrophage infiltration." (PMID 36248827, 2022). "However, because of the limited studies, the function and mechanism of MYD88 in the polarization of M2 and the interaction with glioma cells still need to be further explored." (PMID 33898320, 2021). "Finally, myeloid differentiation primary response 88 (MYD88) was identified as the potential prognostic gene and immune signature of glioma TME and was significantly associated with the higher percentage of M2 macrophages." (PMID 33898320, 2021). "Furthermore, MYD88 was identified to play key roles in the risk model for glioma patients." (PMID 37456890, 2023). "The suppression of GFAP expression was restored by inhibiting the Notch pathway, suggesting that the LPS-induced reversal of glioma differentiation is mediated through the Notch signaling cascade, which is dependent on MyD88." (PMID 40727443, 2025). "In glioma, cell death-related risk signatures (FANCD2, RRM2, BMP2, NFE2F2, MYD88) have been identified and validated using machine learning." (PMID 40559911, 2025). "Combined assessment of the MYD88 L265P mutation, IL‐10 levels and PCR for Ig heavy chain variable (IgVH) rearrangement in the CSF allows efficient discrimination of PCNSL from glial neoplasms and non‐neoplastic disorders of the CNS." (PMID 38836097, 2024). "We constructed a univariate and multivariate cox regression analysis based on ICD-DEGs to identify three genes (FOXP3, MYD88 and IL6) associated with prognosis of glioma patients." (PMID 37456890, 2023). "Immunohistochemistry (IHC) from HPA supported the finding that the protein levels of MYD88 were higher in glioma samples that in normal tissues." (PMID 37456890, 2023). "Glioma cells with high MYD88 levels interacted with macrophage, naïve T cell, microglial cell, and dendritic cell actively." (PMID 37456890, 2023). "Myeloid differentiation primary response 88 (MYD88) has predictive prognostic value by influencing tumor-infiltrating immune cell dysregulation, especially the M2-type macrophages in glioma patients." (PMID 36429083, 2022). "The expression of TLR-4 and MyD88 was increased when LPS was treated with C6 glioma cells, but it was significantly (p < 0.05) diminished in C6 glioma cells treated with non-toxicological levels of IOE (0.1 and 0.2 mg/mL)." (PMID 36670940, 2022). "As regarding MYD88, it was found upregulated in gliomas compared to normal tissues and correlated with unfavorable prognosis." (PMID 36248827, 2022). "This study demonstrated that CSC exosomes, releasing SNHG16, promoted glioma progression by activating the TLR7/MyD88/NFκB/c-Myc signaling pathway, suggesting those markers as possible targets for glioma treatments." (PMID 34638913, 2021).
glioma (continued). "Activation of MyD88-TLR-2 signaling by glioma released factors was found to increase the expression of MMP-9 of microglia." (PMID 34439380, 2021). "LPS from diverse bacteria have been shown to activate distinct MyD88-dependent and -independent pathways in human glioma cells and murine macrophage, although the discriminative capacity was not fully understood." (PMID 33446670, 2021). "The MYD88 expression were significantly lower in normal tissues as compared to the glioma tissues (p = 0.007)." (PMID 33898320, 2021). "MYD88 had predictive prognostic value in glioma patients by influencing TIICs dysregulation especially the M2-type macrophages." (PMID 33898320, 2021). "The level of total STAT3 and phosphorylated STAT3 decreased also when ADV-infected glioma cells were transfected with MYD88 siRNA." (PMID 32843056, 2020). "Western blotting showed that the level of MYD88 decreased in primary glioma cells after siRNA targeting TLR9." (PMID 32843056, 2020). "TLR activation in glioma cell results in signaling through two main pathways, one of which is myeloid differentiation factor 88-independent (MyD88-independent), and the other is myeloid differentiation factor 88-dependent (MyD88-dependent)." (PMID 31661771, 2019). "Notch inhibition reversed the downregulation of GFAP, suggesting that LPS reverses glioma differentiation via the MyD88-dependent Notch pathway." (PMID 31240216, 2019). "All above data indicated that MYD88 was specifically expressed in glioma cells." (PMID 37456890, 2023). "MYD88 was identified and validated to regulate cell proliferation and invasion in glioma cells." (PMID 37456890, 2023). "HPA indicated MYD88 protein levels in glioma tissues were higher than in normal tissues." (PMID 37456890, 2023). "Moreover, to investigate the expression of MYD88 in glioma, we explored the levels of MYD88 in several cell types in malignancies by scRNA-seq." (PMID 37456890, 2023). "The findings suggested the oncogenic roles of MYD88 in glioma." (PMID 37456890, 2023). "MYD88 was considered as prognostic biomarker for glioma patients." (PMID 37456890, 2023). "By single cell RNA sequencing analysis, we could find that MYD88 was specifically expressed in malignant cells not in other cell clusters, enhancing the oncogenic roles of MYD88 in glioma." (PMID 37456890, 2023). "In this study, we also found that a MyD88 inhibitor (NBP2–29328) could ameliorate the LPS-induced expression of inflammatory mediators in C6 glioma cells." (PMID 36670940, 2022). "Curcumin may exert its anti-tumor effects in glioma cells by inhibiting the TLR-4/MYD88 pathway and inducing tumor cell apoptosis." (PMID 36429083, 2022). "Furthermore, IOE (0.2 mg/mL) has similar efficacy to 10 μM of MyD88 inhibitor (NBP2–29328) in recovering the LPS-mediated abnormal expression of inflammatory mediators in C6 glioma cells." (PMID 36670940, 2022). "In addition, IOE attenuated the LPS-induced expression of MyD88 in mouse brains as well as C6 gliomas." (PMID 36670940, 2022). "Furthermore, IOE (0.2 μg/mL) was found to have equivalent efficacy with 10 μM of MyD88 inhibitor in preventing LPS-induced inflammatory responses in C6 glioma cells." (PMID 36670940, 2022). "We also found that IOE could effectively attenuate the LPS-induced activation of TLR-4/MyD88 dependent signaling pathways, resulting in reduced expression of inflammatory mediators in mouse brains and C6 glioma cells." (PMID 36670940, 2022). "These evidences indicate that DNA methylation might participate in the regulation of MYD88 expression in gliomas." (PMID 33898320, 2021). "Further experiments need to be conducted to verify the mechanism of MYD88 in the development of TME of gliomas, which might provide a new target gene and pathway in the treatment as an optional therapy combined with traditional and immunotherapy methods." (PMID 33898320, 2021). "We found that the MYD88 expression was significantly higher in high-grade gliomas." (PMID 33898320, 2021).
glioma (continued). "Furthermore, MYD88 expression was significantly associated with the overall survival and WHO grade of glioma patients." (PMID 33898320, 2021). "MYD88 was found to be an outstanding representative that might play an important role in glioma." (PMID 38847472, 2024). "Besides that, MYD88 was also down regulated in the IDH1 mutant gliomas." (PMID 33898320, 2021). "MYD88 expression was closely tied to the OS and WHO classification of glioma patients, participating in the virulent loop of neoplastic cell evolution and M2 macrophage polarization." (PMID 37153540, 2023). "ROS overproduction induced by LPS treatment was remarkably reduced by NBP2–29328, an inhibitor of MyD88, providing direct evidence that TLR-4 activation is connected with ROS production in LPS-treated C6 glioma cells." (PMID 36670940, 2022). "MYD88 gene played a pivotal role in the TME immune responses by exert influence on the overall survival and histology of glioma patients." (PMID 33898320, 2021). "Then we validated the MYD88 expression both in the CGGA and in Thirty-one glioma patients and found similar results." (PMID 33898320, 2021). "PTEN loss/mutations which are frequently observed in high-grade IDH wild-type glioma can lead to decreased inhibition over TIRAP and consequent upregulation of MyD88-dependent NF-κB activation." (PMID 34715891, 2021). "In glioma, activation of TLR4-mediated MyD88-dependent pathway was reported to correlate with upregulation of NF-κB signaling and increased expression of transcription factors (JUN and SRF), implying promoted cellular proliferation." (PMID 34715891, 2021). "Western blotting showed that the level of MYD88, STAT3 and phosphorylated STAT3 increased in primary glioma cells after ADV infection." (PMID 32843056, 2020). "However, TNFα◽-induced NF-κB activation in glioma cell lines (A172 and LN229) involves both MyD88 and TRIF and is partially dependent on TLR4." (PMID 40727443, 2025). "The levels of MYD88 in tumor samples were much higher than in the non-tumor samples in nine types of cancer including glioma." (PMID 37456890, 2023). "The levels of MYD88 were higher in tumor samples in nine types of cancer than in non-tumor tissues, especially in glioma." (PMID 37456890, 2023). "These indicated that IDH1 mutant might be related with the downregulation of MYD88 expression and less inflammatory responses in glioma TME, which could benefit the prognostics of glioma patients." (PMID 33898320, 2021). "The coinjection of SHG44 and U251 cells with exosomes from SNHG16-overexpressing CSCs into nude mice promoted glioma progression, whereas the inoculation with SHG44 and U251 transfected with si-TLR7 or si-MyD88 reverted those effects by decreasing NFκB activity and c-Myc expression." (PMID 34638913, 2021). "To evaluate whether ADV induced stem-like transformation via MYD88, we synthesized siRNA targeting MYD88, and transfected ADV-infected primary glioma cells." (PMID 32843056, 2020). "However, in glioma cell lines (A172 and LN229), TNFα-induced NF-κB activation is partially dependent on TLR4 and involves both MyD88 and TRIF." (PMID 31240216, 2019). "In addition, since the overproduction of ROS triggered by LPS was ameliorated by IOE treatment in C6 glioma cells, our data suggest that IOE may target the TLR-4/MyD88/ROS/MAPKs or TLR-4/MyD88/ROS/NFκB pathways to prevent LPS-induced neuroinflammation." (PMID 36670940, 2022). "Therefore, ADV infection likely triggers TLR9/MYD88 signaling, which upregulated NEAT1 and activated STAT3, and activated STAT3 further upregulates NEAT1 to form a positive-feedback loop, and promotes GSCs formation from primary glioma cells." (PMID 32843056, 2020).
glioma (continued). "Based on these results, C6 glioma cells pretreated with nontoxic concentrations of IOE (0.1 and 0.2 mg/mL) were evaluated for the LPS-induced expression of TLR-4 and MyD88." (PMID 36670940, 2022). "The function and prognostic value of MYD88 and its related TLRs/IL-1R pathway in TME have not been fully explored in gliomas." (PMID 33898320, 2021).
chronic lymphocytic leukemia (21 papers, 2013 to 2023). "Around 3% of chronic lymphocytic leukemia (CLL) patients have activating mutations of MYD88, a driver mutation in this disease." (PMID 31197259, 2020). "MYD88 L265P is pathogenic, occurring at significant frequencies in hematologic malignancies such as chronic lymphocytic leukemia, marginal zone lymphomas of the ocular adnexa, primary central nervous system large B-cell lymphomas and multiple myeloma amongst numerous others." (PMID 33801781, 2021). "The MyD88-independent pathways of CD180 signaling under pathologic conditions has only been investigated in chronic lymphocytic leukemia cells showing the activation of BTK/PI3K/AKT or p38 MAPK pathways." (PMID 33809015, 2021). "MYD88 mutations in chronic lymphocytic leukemia (CLL) are not well characterized." (PMID 32848129, 2020).